C15orf32 (chromosome 15 putative open reading frame 32)
Synonyms: FLJ32831
Gene: Long non-coding RNA gene on chromosome 15 (92,471,654 to 92,501,119, forward strand). Ensembl gene ENSG00000183643.
Diseases named in the same sentence as C15orf32 in open-access papers:
C15orf32 is named in the same sentence as 2 diseases in open-access papers, as found by Europe PMC text mining. Sharing a sentence is not in itself a finding about the gene and the disease. The quoted sentences say what the papers report.
bipolar disorder (1 paper, 2012). A disorder of the brain that causes unusual shifts in mood, energy, activity levels and the ability to carry out day-to-day tasks. "Moreover, a GWAS of bipolar disorder in Han Chinese found strong association (P<6×10−6) with two SNPs which lie 30 kb downstream of ST8SIA2 in the C15orf32 gene." (PMID 22693595, 2012).
depression (1 paper, 2012). "An association study of 15q25-26 for recurrent early onset depression showed nominal association with NTRK3 and the genes flanking ST8SIA2: SLCO3A1 and C15orf32; but not ST8SIA2 itself." (PMID 22693595, 2012).